TNF (tumor necrosis factor)
Diseases named in the same sentence as TNF in open-access papers (continued):
Sharing a sentence is not in itself a finding about the gene and the disease.
infection (continued). "Memory and functional profiles induced upon early infection were sustained at stable proportions once M.tb infection is established, with the exception of highly differentiated KLRG-1+IFN-γ+TNF+ TE cells, which were more abundant during persistent QFT+ compared to recent QFT conversion." (PMID 33610126, 2021). "Both TNF-α and IL-6 are critical proinflammatory cytokines against pathogen infection, and a lack of TNF-α and IL-6 results in higher mortality and more susceptibility to bacterial infection." (PMID 34564598, 2021). "Furthermore, IL-1beta and TNF alpha have been shown to induce the acute release of ACE2, which supports the protective role of ACE2 against spike-driven infection and ADAM10 regulation of ACE2 cleavage." (PMID 34356057, 2021). "Unfortunately, given the survival data of mice infected intratracheally and the decreased levels of TNF-α in the brain, the stimulation of the lung proinflammatory immune response was not sufficient to clear the infection." (PMID 33103620, 2020). "Both the TNF-α mRNA level in PRRSV+ICs-infected cells and its protein level in culture supernatants of PRRSV+ICs-infected cells were also significantly downregulated at any time point post-infection, compared to PRRSV+PNI-infected cells." (PMID 32046249, 2020). "Taken together, this set of data suggests that only H. pylori wt, but not the ΔCagPAI mutant, is able to induce TNFα expression within 1 h of infection, which in turn activates the expression of SOCS3 mRNA." (PMID 33023610, 2020). "The resulting iDCs were either infected with HSV-2 strain G or HSV-1 as control, and harvested at 2, 4, 8, or 16 hpi or matured into mDCs, via stimulation with a maturation cocktail, additionally containing IL-1β, IL-6, TNF-α, and PGE2, followed by the same infection procedure as for iDCs." (PMID 31963276, 2020). "At 12 and 36 h post-infection, no intervendor differences were found in bacterial dissemination, or TNFα and IL-6 levels in the lungs." (PMID 32840685, 2020). "Furthermore, the observed abundances of mRNA related to T cell responses also indicated Th1 cell-related molecules (TNF-α and IFN-γ) were significantly activated early in an infection." (PMID 33520738, 2020). "In addition, infection of C57BL/6 mice with L. major leads to enhanced release of the TH1-inducing cytokines IL-12, IL-1β and TNF in the infected skin." (PMID 33584721, 2020). "In lung tissues, the TNF-α, IL-1β and IL-6 levels in the positive control group were all significantly higher compared with the negative control group at 72 h after infection." (PMID 33551807, 2020). "Thus, TLR4, IL27, and TNF were activated across all groups; IFNG was exclusively activated by AMTB-127 and AMTB-205; PTGS2 was activated in AMCTs and AMTBs in response to infection with Mtb UT205, whereas TLR2 was only activated in response to Mtb UT127." (PMID 32373118, 2020). "The infection with S. Typhimurium induced the appearance of all inflammatory cytokines in blood plasma and allowed to count the IL-10/TNF-α ratio in contrast to all groups of non-infected piglets with nonmeasurable cytokines." (PMID 33333934, 2020). "While an early activation of interferon α/β signaling was observed, several innate immune signaling pathways including TLR, TNF, NF-κB, and NOD-like receptor signaling and key inflammatory cytokines such as Il-1α, Il-1β, and TNF typically activated following infection were suppressed." (PMID 32722194, 2020). "In the V+H1N2var group, the mean concentrations in haptoglobin, IL-6, and TNF-α have not been changed as compared to the Control group either, but individual responses to the infection appeared to be heterogeneous, as shown by the large standard deviations." (PMID 33053905, 2020).
infection (continued). "In the present work, samples obtained after 45 days of infection revealed that diabetic mice still presented signs of strong ongoing inflammation, characterized by high IFN-γ levels and a high TNF-α:IL-10 ratio, whereas this inflammation was found to be subsided in the nondiabetic groups." (PMID 33312173, 2020). "In a retrospective observational cohort-study, our group evaluated the role of methotrexate, corticosteroids, and TNF-α antagonists alone or in combined therapy on non-serious and serious infections in RA and spondyloarthritis (SpA) patients." (PMID 32397174, 2020). "Besides being important to kill the parasite, when in excess, TNF-α, IFN-γ and iNOS contribute to myenteric plexus degeneration during T. cruzi experimental infection." (PMID 32986710, 2020). "In support of this notion, in a mouse model of infection with non-typeable haemophilus influenzae, the aspirin triggered RvD1 decreased the concentration of pulmonary TNFα and IL-6 in addition to driving the clearance of macrophages." (PMID 32983141, 2020). "The infection of adult immunocompetent mice with H. pylori significantly increased the levels of the inflammatory factors IFN-γ, TNF-α, MCP-1 and IL-8, as well as the levels of the regulatory cytokine IL-10 when compared to basal levels in non-infected animals (data not shown)." (PMID 32230910, 2020). "Infection by the low-virulence isolate Nc-Spain1H triggered an increase in the expression of important pro-inflammatory cytokines such as IL-1β, IL-8, IL-12p40, IFN-γ, TNF-α and iNOS as early as 10 dpi (P < 0.1–0.001)." (PMID 32552750, 2020). "Further, sTNF-deficient transgenic mice that express a non-cleavable form of TNF were partially protected against infections with the pathogens Mycobacterium tuberculosum and Listeria monocytogenes." (PMID 32528961, 2020). "However, TNF-α, IFN-γ, and IL-6 levels were significantly increased in T. cruzi A and BALB/c infected mice when compared with the control groups through the infection." (PMID 33329529, 2020). "After the infection of SARS-CoV-2, the activated monocyte-derived macrophages can release massive amounts of pro-inflammatory cytokines such as interleukin (IL), tumor necrosis factor (TNF)." (PMID 33193019, 2020). "Among 27 cytokine proteins included in this study, 9 cytokines (TNF-α, IL-8, MIP-1α, MIP-1b, MCP-1, RANTES, IL-1rα, IL-9, IP-10) were found at measurable levels in culture supernatants of PHHs following mock infection and/or DENV-2 infection at MOI of 5 for 48 h." (PMID 33216752, 2020). "In addition, there was attenuated intestinal tumor necrosis factor alpha (TNF-α) and interferon gamma (IFN-γ) responses during infection with the ΔcadF mutant compared to the wild-type strain." (PMID 32168837, 2020). "IFN-γ became high in asymptomatic infection but became low on conversion, whereas, no significant change in level of TNF-α was observed at both stages of disease." (PMID 32555598, 2020). "In addition, an increase in TNF-α, IL-6, IL-10 and VEGF levels were measured at 6 h and 24 h post infection." (PMID 32316163, 2020). "TNF-α levels were significantly elevated by 5.7-fold (1,040 ± 227.4 pg/mL) in HIV infected MG-hBORGs compared to mock-infected (196.8 ± 48.7 pg/mL) at early infection (day 3)." (PMID 32938988, 2020). "Although the CSF tested negative for organisms (data not shown) 10 days after the infection, the levels of TNF-α (P < 0.05) were still high in the PFC compared to the respective control groups, with a simultaneous decrease in IL-12 and IL-17 (P < 0.05)." (PMID 31901235, 2020). "At the site of infection, infected cells produce chemokines and cytokines such as type I IFNs, IL-6, IL-8, TNF-α, CCL2 (MCP-1), RANTES, and MIP-1α that recruit immune cells including NK cells, neutrophils, macrophages and DCs to the site of infection where they initiate the innate immune response." (PMID 32375274, 2020).
infection (continued). "Moreover, the decreased levels of TNF-α, IL-6, IL-8 and IL-β in LPS+si-NEAT1 group were overturned following infection with anti-miR-370-3p." (PMID 32414769, 2020). "In addition, monocyte-macrophage mediated production of proinflammatory cytokines IL-6, IL-1β, tumor necrosis factor (TNF) and chemokines enable the recruitment of neutrophils and other inflammatory immune cells to the site of infection." (PMID 33510644, 2020). "Although heightening the TNF-α response appears contradictory to a protective role of BMP9, we suggest this promotes a more effective acute response in the context of tissue damage or infection." (PMID 32576665, 2020). "Strikingly, even systemic C. jejuni induced pro-inflammatory cytokine responses were dependent on an intact pepP gene, given that IFN-γ, TNF, MCP-1, and IL-6 concentrations were lower in serum samples following ΔpepP versus WT and pepP complemented strain infection (p < .05–0.01)." (PMID 32584649, 2020). "Enhanced expression of acute and chronic cytokines, such as IL-1β, TNF-α, and MIP-1α was also detected, especially in the lung (the initial infection site), and spleen (a representative tissue of systemic immunity) of the transgenic mice following challenge with MERS-CoV." (PMID 31838832, 2020). "TNF-α, IL-6, CXCL10, and IFN-β were induced after infection with all three viruses." (PMID 32849329, 2020). "Accordingly, Siglece−/− mice produced more IL-6 and TNF-α than wild-type littermates after infection with E. coli 25922 or DH5α but not with S. aureus or L. monocytogenes." (PMID 32889432, 2020). "We measured TNF-α, IL-6, IFN-γ, IL-17A and IL-10 after an experimental intravenous infection with S. suis serotype 2 in vivo, and analyzed whole blood, peripheral blood mononuclear cells (PBMC) and separated leukocytes to identify the cytokine-producing cell type(s)." (PMID 31947746, 2020). "At three days after treatment, amphenmulin could significantly decreased TNF-α, IL-6, and MCP-1 in the serum in comparison to those of the infection group, avoiding the adverse effects of excessive inflammatory factors on wound healing." (PMID 32079232, 2020). "The TNF-α increase observed in UC- or CD-derived MDM in the presence of probiotic strains was not due to their ability to promote TNF-α secretion, as MDM infection with probiotic strains alone resulted in non-detectable levels of TNF-α." (PMID 32752244, 2020). "Following infection of differentiated THP-1 cells with Bt at an MOI of 1, treatment with TLR4-ab–compared to an isotype control–significantly reduced supernatant TNF-α concentrations in the presence of rhLTF (p = 0.03) or phLTF (p = 0.008), but not media alone." (PMID 32764765, 2020). "MAYV infection induced acute production of several pro-inflammatory molecules in the spleen such as IL1-β and IL-6 from days 1 to 7 of infection; IFN-γ from days 1 to 5 and finally, TNF-α at the early time-points of 1 and 3 days post-MAYV inoculation." (PMID 32210270, 2020). "However, HIF-1α can also be stabilized and activated under normoxic conditions in a variety of situations, including contact with inflammatory cytokines (TNF-α, IL-6 and VEGF), exposure to ROS, cyclic mechanical stretch in vitro or by MV in vivo and infection." (PMID 32353952, 2020). "Both Th1 and Th17 T cells expressed TNFα and IL-2, but then progressed to also express IFNγ at day 7 post infection (which show day 14 post infection in both vaccinated and nonvaccinated mice having received a dose of 103, or even 102 IFUs)." (PMID 31993218, 2020). "In this study, an ADE assay showed that PRRSV-ADE infection in porcine alveolar macrophages (AMs) significantly decreased the production of interferon-α (IFN-α) and tumor necrosis factor-α (TNF-α), and significantly increased the production of interleukine-10 (IL-10)." (PMID 32046249, 2020).
infection (continued). "However, the expression of IL-10 and TNF-α in the gastric mucosa was positively correlated with the HbA1c levels, suggesting that inflammatory and anti-inflammatory markers released in the gastric mucosa during infection by H. pylori may be involved in the disturbance of glucose metabolism." (PMID 33013895, 2020). "In miiuy croaker brain cells (MBrC), MAVS-specific siRNA could also significantly suppress the expression of IFN-2, TNF-α, Mx1, and ISG15 upon SCRV infection." (PMID 32678830, 2020). "However, TNF-α-expressing cells were maintained in both blood and BAL after infection, suggesting that MAIT cells retain some functionality even after SIV infection." (PMID 32572140, 2020). "Although the innate and adaptive immune effector cells can directly destroy the infected liver cells, much of the antiviral ability of these cells results from production of antiviral cytokines at the site of infection, such as interferon-gamma (IFN-γ) and tumor necrosis factor-alpha (TNF-α)." (PMID 32664850, 2020). "Subsequently, we sought to examine the influence of Ss infection on the systemic levels of Type-1 (IFN-γ, TNF-α, and IL-2), Type-17 (IL-17A and IL-22), Type-2 (IL-4, IL-5, and IL-13), regulatory (IL-10) and pro-inflammatory cytokines (IL-1α, IL-1β, IL-6, IL-12, and GM-CSF) in INF and UN individuals." (PMID 33042134, 2020). "Although SAHA promoted TNF production in the context of iH37Rv stimulation, it did not increase TNF production in the context of infection with H37Ra." (PMID 32793237, 2020). "In MBrC cells, knockdown of MARL could also significantly inhibit the expression of IFN-2, TNF-α, Mx1, and ISG15 upon SCRV infection." (PMID 32678830, 2020). "Similarly, our investigation showed that the decreased levels of TNF-α, IL-6, IL-8 and IL-β in LPS-induced RAW 264.7 and HL-1 cells were inverted after the infection with miR-370-3p inhibitor." (PMID 32414769, 2020). "Infection of macrophages with MAP increased iNOS expression (13.09 ± 0.94 vs. 5.11 ± 0.8 in uninflected cells), IL-6 (38.43 ± 1.2 vs. 18.5 ± 1.8 in uninfected cells), and TNF-α (0.54 ± 0.075 vs. 0.27 ± 0.08 in uninflected cells)." (PMID 32370298, 2020). "Infection resulted in immune-cell activation, with upregulation of cell surface activation markers (e.g., CD80, PD-L1, HLA-DR) and secretion of proinflammatory cytokines (IFN-α2a, IL-6, IL-8, TNF-α)." (PMID 32088771, 2020). "In addition, the percentage of neutrophils (GR-1) that were TNF-α+ peaked 2 days after vaccinations with mc2-CMX and BCG while mc2-CMX vaccination remained with increased levels at 7 days post infection when compared to saline and BCG." (PMID 32391021, 2020). "We demonstrate that myeloid cells are the natural source of TNF that triggers apoptosis in either myeloid (autocrine) or non-myeloid cells (paracrine) during ∆M36 infection of mice." (PMID 33126536, 2020). "On the next day after infection, an upregulation of iNOS and TGF-β could be observed in C57BL/10 mice followed by an increase of those genes and the inflammatory cytokines TNF-α, IFN-γ, and IL-12, 30 days after infection." (PMID 32983013, 2020). "Differential gene expression in implanted CT26 tumors treated with mVG161 compared to equivalent tumors injected with VG160 revealed that infection with mVG161 bearing IL-12, IL-15, and IL-15RA transgenes powerfully stimulates a prototypical Th1 immune response (e.g., IFN-γ, TNF, and IL18)." (PMID 33182232, 2020). "Similar changes were also seen in TNF-α levels in TLR4 −/− mice, which may be due to the complexity of the inflammatory response network after infection." (PMID 32098158, 2020). "At later times of infection, iNOS expression is induced by IFN-γ in combination with TNF." (PMID 32983013, 2020). "Anti-TNF treatment of TNF gene deletion had no impact on K181 infection but dramatically rescued ∆M36-induced apoptosis." (PMID 33126536, 2020).
infection (continued). "In the assessment of TNF in adipose tissue showed that regardless of infection, the high-fat diet stimulated high production of this cytokine." (PMID 32596277, 2020). "We noticed that TNF levels did not increase further after 24 h of infection compared to their levels after 6 h." (PMID 32799619, 2020). "Similarly, infection of the RG virus NS1680 stimulated a higher level of IFN-β and TNF-α in chicken DF1 cells, whereas cells infected with RG NS683 virus expressed a lower level of TNF-α in DF1 cells." (PMID 32226416, 2020). "Testicular macrophages are infected by ZIKV, and the infection promotes an increase of mRNA transcript levels of the IFN-α and IFIT1 genes, inducing the secretion of pro-inflammatory cytokine TNF-α, IL-1α, and IL-8 and chemokines, such as GRO, IP-10, and monocyte chemoattractant protein 1 (MCP-1)." (PMID 32325652, 2020). "The constitutively expressed cytokines IL-1α and TNF-α were elevated already in early stages of the infection, whereby TRP was able to significantly reduce their gene expression 24 h and 48 h post infection." (PMID 32024909, 2020). "Our results showed that the hippocampus of TB mice exhibited a highly significant increase in the expression of the pro-inflammatory (TNFα, IFNγ, IL12) and anti-inflammatory cytokines (IL4, TGFβ), as well as the enzymes iNOS and IDO from day one post-infection." (PMID 33322180, 2020). "The MHC expression levels are, however, not strictly maintained and can be modulated during infection by immune regulators such as interferon and tumor necrosis factor (TNF)." (PMID 33013938, 2020). "To confirm this hypothesis, we induced moDCs with TNFα to analyze its capacity to induce SOCS3 mRNA expression and, additionally, we blocked TNFα in DCs using a neutralizing antibody prior to infection." (PMID 33023610, 2020). "This correlates with the ability of S. negevensis to block TNFα-, but not staurosporin-induced cell death up to 3 days post infection, after which cell death is boosted by the presence of bacteria." (PMID 33194844, 2020). "In the human assay, secretion of IFN-γ, TNF, and MIP-1β correlated to control of infection." (PMID 32365846, 2020). "Apparently, basal expression of TNFα in most of the tissues/brain areas examined in grass carp (i.e., without experimentally induced infection/inflammation) is rather low/undetectable." (PMID 32082258, 2020). "Experimental infection in rodents with various strains of P. gingivalis have been shown to increase maternal serum levels of TNF, IFN-γ, and IL-1β along with FGR10,13,15, which we did not see in our model." (PMID 32884071, 2020). "Interestingly, PMNs treated with a combination of IFN-γ and GM-CSF increased the production of TNF-α in response to R. microsporus and L. corymbifera, while incubation with only IFN-γ suppressed PMNs’ ability to release IL-8 after infection with these fungi." (PMID 32957440, 2020). "Our findings showed significant increases in the levels of IL-6, TNF-α, INF-γ, MCP-1, and NO late in disease progression, which may have contributed to cell death and lymphocytic infiltration at the end of infection." (PMID 32294697, 2020). "When compared to non-infected patients, patients developing an infection had a reduced immunoresponsiveness, reflected by decreased TNF-α values after ex vivo bacterial stimulation." (PMID 33237337, 2020). "The cytokines CXCL8, CCL5 (also known as Regulated on Activation, Normal T Expressed and Secreted, RANTES), tumor necrosis factor α (TNF-α), CXCL1/5 and CCL3 released, promote development of a pro-inflammatory state along with the recruitment of other immune cells to the site of infection." (PMID 33102253, 2020).